TNFSF15 (TNF superfamily member 15)
Diseases named in the same sentence as TNFSF15 in open-access papers (continued):
Sharing a sentence is not in itself a finding about the gene and the disease.
cancer (continued). "In addition, the analyses of forty-five immune stimulators showed that METTL1 expression was positively related to TNFRSF18 as well as negatively associated with TNFSF15 and IL6R in nearly all cancers." (PMID 35432338, 2022). "The TNFSF15 gene is involved in the development of a variety of cancers." (PMID 34859010, 2021). "Collectively these findings suggest an important role of TNFSF15 in cancer suppression." (PMID 25251497, 2014). "In addition, many studies have reported the roles of TNFSF15 SNVs in cancer development." (PMID 36226563, 2022). "We identified multiple TNF superfamily members with direct apoptotic effects on cancer cells, including TNFSF10 (TRAIL), TNFSF14 (LIGHT), TNFSF15 (TL1A), and LTA." (PMID 40564222, 2025). "In most cancer types, CD274 (PD-L1), NRP1, and TNFSF15 were positively correlated with YAP1 expression." (PMID 36479120, 2022). "Additionally, USP37 demonstrated a significant positive relationship with ADORA2A, CD160, TNFSF15 and NRP1 across the majority of cancers." (PMID 40926837, 2025). "An additional investigation demonstrated an age-dependent correlation of TNFSF15, which was observable not solely in individuals with cancer but also in those with other ailments related to the immune system." (PMID 38590525, 2024). "In diverse cancer types, the correlation between OAS3 and the expression of checkpoint genes indicated a high correlation with TNF-related immune genes including TNFRSF14, TNFRSF8, TNFRSF25, TNFRSF4, TNFRSF18, TNFSF15, and TNFRSF9." (PMID 35592250, 2022).
infection (19 papers, 2009 to 2025). The state of being infected such as from the introduction of a foreign agent such as serum, vaccine, antigenic substance or organism. "We found that the expression of eight genes, including Il18, Il36b, Il17rc, Tnfsf10, Tnfsf11, Tnfsf14, Tnfsf15, and Il1a, were closely correlated with the severity of HAdV-55 infection." (PMID 30787914, 2019). "Differential changes in the expression of CCL19, CCL20, IL-8, IL-15, and Trail/TNF (ligand) superfamily members TNFSF10 and TNFSF15 in DT40 cells were also observed at different time points after vvIBDV infection." (PMID 28086922, 2017). "Recently, several studies have investigated the important role of TNF superfamily (such as TNFSF-15) and IL-17 family (such as IL-17F) in the regulation of immune response during infection of Eimeria." (PMID 22754694, 2012). "Infection (NC group) with E. maxima increased the gene expression of TNFSF15 (p = 0.006, 2.9 × 10−3 to 2.3 × 10−2), IL-1β (p = 0.001, 1.9 × 10−3 to 4.9 × 10−3), and IL-8 (p = 0.022 6.3 × 10−3 to 2.0 × 10−2) in the distal jejunum compared to that of the CON group." (PMID 35812452, 2022). "Additionally, TNFSF11 and TNFSF15 was expressed at lower levels after infection." (PMID 31725732, 2019). "During early-phase infection, there was robust upregulation of pro-inflammatory cytokines such as JUN, IL15, ATF2, TNFSF15, and CXCL10, indicating strong immune activation." (PMID 40649996, 2025). "Further transcriptomic analysis revealed that the Tnfsf15 gene plays a critical role in the regulation of A909 strain pathogenicity mediated by the BP, AP1, and SrtC gene clusters during host infection." (PMID 40611352, 2025). "For the cell host response in the early-phase infection, genes such as JUN, IL15, ATF2, TNFSF15, and CXCL10 were significantly upregulated, reflecting a strong pro-inflammatory and immune response." (PMID 40649996, 2025). "These were accompanied by activation of genes related to cytokine production, including TGFB, CXCL6, TNFSF15 and XCL1, which prompt the recruitment of immune cells to the location of an ongoing infection." (PMID 36178892, 2022). "At 6 h post-infection this trend continued, and several other members of the TNF-α superfamily were also up-regulated: TNFSF9, TNFSF10 and TNFSF15 (all at least 1.7-fold higher in H5N1-treated cells)." (PMID 20011590, 2009). "In the absence of maltol, infection (NC group) with E. maxima increased (P < 0.05) the gene expression of TNFSF15 (3.4 × 10−3-2.3 × 10−2), IL-1β (1.9 × 10−3-4.9 × 10−3), and IL-6 (3.0 × 10−3-9.9 × 10−3) in the distal jejunum compared to that of the CON group." (PMID 34095279, 2021). "Minimum adequate models (MAMs) for effects of infection with Mycoplasma gallisepticum isolates VA1994 and NC2006 on house finch expression of cytokines IL1B, IL6, IL10, CXCLi2, and TNFSF15 in internal eyelid (nictitating membrane) across three different time points." (PMID 29403495, 2018).
bacterial infection (3 papers, 2017 to 2025). "TNFSF15, also known as TNF ligand-related molecule 1, contributes to the innate and adaptive immune response in mucosal tissues against bacterial infections by binding to its specific receptor." (PMID 37799512, 2023). "Furthermore, Tnfsf15 has been shown to play an important proinflammatory role in various bacterial infections." (PMID 40611352, 2025).
degenerative diseases (1 paper, 2020). "Our research suggested that TNFSF15 may thus be useful for acquiring HSC from umbilical cord blood for the treatment of haematological malignancies and degenerative diseases." (PMID 32910534, 2020).
TNFSF15 also shares sentences with these, for which no sentence is quoted: liver fibrosis (6 papers); inflammation (5); primary biliary cirrhosis (5); Arthritis (4); Chronic colitis (4); fibrosis (4); infectious disease (4); experimental autoimmune encephalomyelitis (3); uveitis (3); acute coronary syndrome (2); Behçet's disease (2); chronic lymphocytic leukemia (2); deafness (2); experimental arthritis (2); Intestinal Diseases (2); lung fibrosis (2); multiple sclerosis (2); oral cancer (2); sarcoidosis (2); acute respiratory distress syndrome (1); allergic reactions (1); arthropathy (1); autoimmune uveitis (1); Autoimmunity (1); B-cell lymphoma (1); bladder carcinoma (1); brain injury (1); childhood asthma (1); chronic liver failure (1); colorectal adenocarcinoma (1).
A further 44 diseases each share a sentence with TNFSF15 in 1 paper.